CASP1 (caspase 1)
Diseases named in the same sentence as CASP1 in open-access papers (continued):
Sharing a sentence is not in itself a finding about the gene and the disease.
tumor (continued). "Interestingly, dual incubation with LPS and a caspase-1 inhibitor ablated the increase in tumour cell adhesion to endothelial cell monolayers and was associated with a large reduction (62–83%) in the amount of IL-1β present in the macrophage-conditioned media." (PMID 28551814, 2017). "To further investigate the molecular mechanism underlying caspase-1-mediated tumoricidal effect, we first tested whether IL-1β and IL-18, two downstream cytokines of caspase-1 (refs 38, 39), contributed to PsV-induced tumour regression." (PMID 28397782, 2017). "In addition, we found a significant increase in the expression of CASP1 in basal and luminal B type tumours in obese patients." (PMID 27708283, 2016). "CASP1 expression was also upregulated in these types of tumours from overweight patients." (PMID 27708283, 2016). "2.5 × 105 EO771 tumor cells were injected orthotopically into the 4th fat pads (murine mammary glands) of wild type (WT) and caspase-1 knockout (KO) female mice (all on the C57BL/6 background) at about eight weeks old, then tumor growth was measured once every two days." (PMID 27786298, 2016). "However, it is still unclear how tumors manage to effectively utilize the tumor promoting functions of the ATP/HMGB1/caspase-1 system while successfully evading immune-mediated destruction." (PMID 26552848, 2015). "The role of inflammasomes in carcinogenesis is contrasting; they may inhibit tumor promotion by activating caspase-1 and cell killing, or may promote tumor growth by upregulating secretion of pro-inflammatory molecules like, IL-1β, IL-18, FGF2 and HMGB1." (PMID 26689911, 2015). "Tumor growth and survival is therefore critically dependent on an optimal balance between the pro-survival and cytotoxic functions of purinergic signaling and caspase-1." (PMID 26552848, 2015). "All these results suggest that tumor cells are characterized by a particular LXRβ localization, and that this localization makes cells sensitive to treatment with T0901317, which activates caspase-1." (PMID 26450852, 2015). "Moreover, it has been shown that Il18−/− or Il18r−/− mice are more susceptible to DSS-induced colitis and CRC, mimicking the increased tumor burdens observed in NLRP3 and caspase-1 deficient mice." (PMID 25071785, 2014). "Similarly to caspase-1 deficient mice, NLRC4 knockout mice features significantly enhanced proliferation in both steady state and the early phase of inflammation-induced tumor formation." (PMID 23606794, 2013). "Notably, caspase-1 inhibition could partially restore tumor growth, which is otherwise impeded by Sorcin knockdown." (PMID 41291696, 2025). "However, a comparative study assessing NLRP3 (NOD-like receptor protein 3), caspase-1, IL-1β, and IL-18 mRNA and protein expression in hen and human OvCa found increased protein expression of caspase-1, IL-1β, and IL-18 in surface epithelium, tumor cells, and immune cells." (PMID 40718836, 2025). "The induction of caspase-1 in HCT-116 suggests that 12 may trigger an inflammatory response that contributes not only to direct cytotoxicity but also to a potential immunogenic effect within the tumor microenvironment." (PMID 41155897, 2025). "The ASC adaptor protein, as well as the caspase-1 effector, may be involved in tumor progression." (PMID 39684769, 2024). "This study confirmed that lack of NLRP3 inflammasome is involved in HCC progression and 17β-estradiol-induced activation of NLRP3 inflammasome may be effective in HCC treatment as it inhibited tumor cell growth and proliferation by triggering CASP1-dependent pyroptosis in HCC cells." (PMID 36763290, 2023). "A previous study reported that CASP1 assists in regulating T cell immunity and innate immunity in three pyroptosis‐related regulators of PS‐related signature, which might indicate their important roles in tumor checkpoint inhibition." (PMID 36161280, 2023).
tumor (continued). "Nlrp3-/- mice developed atypical hyperplasia and tumor formation due to elevated inflammatory responses and disruption of the intestinal epithelial barrier in response to CRC induction by (AOM)/dextransodium sulfate (DSS) and similar results were observed in ASC and caspase-1 deficient mice." (PMID 37081882, 2023). "Moreover, the inflammatory environment and related substances that are ubiquitous in the tumour environment, such as ATP released after cell death, can easily activate the NLRP3 inflammasome pathway and cleave gasdermin D (GSDMD) by activating caspase-1 and cause tumour-cell pyroptosis." (PMID 35289335, 2022). "Moreover, the abundant flagella of VNP could activate the caspase 1 to transform the delivered GSDMD proteins into the active form for triggering tumor cell pyroptosis." (PMID 36280674, 2022). "Interestingly, similar phenomena were observed in both prostate and OCs, suggesting that targeting caspase-1 may be a new approach to tumor therapy." (PMID 34773569, 2022). "This may suggest that activated caspase-1 is associated with the initiation of inflammatory programmed cell death (pyroptosis) and, in turn, inhibits tumor growth rather than upregulating pro-inflammatory molecules such as IL-1β and IL-18." (PMID 35883451, 2022). "Thus, our data uncovered a novel mechanism that DDP induced pyroptosis via activation of MEG3/NLRP3/caspase-1/GSDMD pathway in TNBC to exert anti-tumor effects, which may help to develop new strategies for the therapeutic interventions in TNBC." (PMID 34326697, 2021). "However, several reports also pointed out that the proinflammatory effect of caspase 1 may on the other side facilitate tumor progression." (PMID 34820372, 2021). "The expression level of Caspase-1 may be related to the degree of inflammation in tumor tissues." (PMID 33741902, 2021). "However, the role of CASP1 in tumor autophagy is still unclear." (PMID 33777735, 2021). "The inflammasome/IL-1 pathway is an important mechanism in the development of BC lung metastasis, as confirmed by the significant reduction of lung metastasis in inflammasome or caspase-1-deficient mice, and may be related to IL-1β-induced expression of CCL2 in macrophages and tumor cells." (PMID 34602858, 2021). "Therefore, caspase-1-mediated programmed cell death may remove tumour cells and suppress tumour progression, but improper and excessive activation may promote carcinogenesis through suppression of immune surveillance." (PMID 33918087, 2021). "Therefore, our findings demonstrate that DHA may act as a RalB inhibitor to regulate the crosstalk between autophagy and IFI16/caspase-1 inflammasome, which inhibits IL-1β production in tumor microenvironment." (PMID 32577124, 2020). "Moreover, KC disappearance associated with caspase-1 activity induced the recruitment of monocyte-derived cells that are beneficial for tumor growth, while caspase-8-dependent reduction did not." (PMID 33178579, 2020). "Therefore, targeting the caspase-1/PPARγ/MCAD pathway might be a promising therapeutic approach to prevent tumor progression." (PMID 28974683, 2017). "In addition, we cannot completely exclude the possibility that PsV-induced caspase-1 activation might somehow shape the composition of gut microbe community that might contribute to tumour regression." (PMID 28397782, 2017). "Finally, modulating MCAD activity in TAMs through treatment with caspase-1 inhibitors or genetic manipulation suppressed primary tumor growth in in vivo mouse models, thus supporting potential clinical applications for targeting the caspase-1/PPARγ/MCAD pathway in TAM differentiation." (PMID 28974683, 2017). "To investigate whether repression of CASP1 expression is necessary for G9A-mediated cell invasion and migration, we transiently overexpressed CASP1 in PC9 and A549 cells, and found that CASP1 overexpression significantly inhibited tumor cell invasion and migration abilities in these cells." (PMID 28383547, 2017).
tumor (continued). "In this study, only ASC, but not the other inflammasome-associated molecules NRLP3, CASP1 and IL-1β was strongly associated with the clinicopathological characteristics (e.g. tumor stage and node stage) and was an independent predictor of OS, DSS, and DFS of OSCC patients." (PMID 27367024, 2016). "Caspase 1 and Annexin-V were significantly decreased in FliiTg/Tg SCCs compared to wild-type and Flii+/− mice tumors suggesting that high Flii levels may aid in tumor evasion of apoptosis in Flii overexpressing mice." (PMID 26497552, 2015). "The IL-18 cytokine, cleaved into its biologically active form by activated caspase-1, has emerged as a key cytokine downstream of inflammasome activation that enables epithelial repair after damage, but also prevents cancer progression through its induction of the tumor suppressors STAT1 and IFN-γ." (PMID 24795727, 2014). "Experimental inhibition of NLRP3 or caspase-1 has been shown to suppress OSCC cell migration, invasion, and proliferation, underscoring the contribution of NLRP3 inflammasome signaling to tumor progression." (PMID 41596738, 2026). "In NSCLC, caspase-1 drives pyroptosis through the GSDMD–NLRP3 pathway, amplifying inflammatory responses and potentially limiting tumor progression." (PMID 40555741, 2025). "NBS-1MT triggered pyroptosis by activating the caspase-1/GSDMD signaling pathway, leading to the suppression of primary and distant tumor growth." (PMID 40698137, 2025). "Immunofluorescence staining indicated that expression levels of C-Caspase-1, N-GSDMD, and NLRP3 were significantly elevated in tumor tissues treated with THZO NWs, with even greater enhancement in the THZO + US group." (PMID 41402300, 2025). "The results showed elevated levels of AIM2 in tumor tissues, while CASP1, NLRP3, and NLRP1 exhibited low expression in these tumor tissues." (PMID 40026444, 2025). "Mechanistic studies involved the levels of cellular ROS, IL-1β, IL-18 and the expression of caspase-1/3/7/9-GSDMD/E in both cell and tumor tissues were determined by ELISA, immunohistochemistry, Western blot and qRT-PCR." (PMID 40604924, 2025). "Our analysis revealed distinct expression patterns of CASP1, FOXP3, and PDIA3 between normal and tumor tissues, highlighting their potential roles in shaping the tumor immune microenvironment." (PMID 41150760, 2025). "Further analysis of the differential expression of IL-1 family and related genes in normal tissues and HPV- and HPV+ tumor tissues revealed that IL-1α, IL-1β, IL1R1, IL1R2, IL1RL1, IL1RAP, IL1F10, IL-18 and CASP1 were highly expressed in HPV- tumors." (PMID 39461030, 2024). "On the other hand, no statistically significant but slightly decreased profile of both caspase-1 and IL-1β in contact with PTX before and after NLRP3 knock-down demonstrated the ability of PTX to stimulate tumor cell death." (PMID 39433537, 2024). "As a result, caspase-1 inhibitors, such as VAD, YVAD, and NCX-4016, are able to reprogram TAMs into an anti-tumor phenotype and prevent tumor growth in vivo." (PMID 39169402, 2024). "In CRC models, RT suppressed the expression of miR-15a while inducing caspase-1 activity and GSDMD expression, decreasing tumor cell vitality, proliferation, and growth." (PMID 39062587, 2024). "Regarding caspases, tumor cells exhibited predominantly high expression of CASP4, and immune cells showed high expression of CASP1, CASP4, and CASP8, while CASP5 plays an important role in stromal cells." (PMID 38229080, 2024). "ATP from the pyroptosing tumor cells subsequently activates the NLRP3 inflammasome in macrophages, resulting in caspase-1 activation and downstream GSDMD and IL-1β processing and release." (PMID 38391959, 2024).
tumor (continued). "The mRNA relative expression level of NLRP3, Caspase 1, GSDMD, IL-1β and IL-18 in XRZYBXD high dose group were significantly higher than those in the tumor model group by Q-PCR." (PMID 40046008, 2024). "Hydrogen is also likely to alleviate tumor volume and weight in the xenograft mouse model through the ROS/NLRP3/caspase-1/GSDMD-mediated pyroptotic pathway." (PMID 39011036, 2024). "To that end we have shown that caspase-1-dependent IL1β production is a defining feature of TNBC that drives the recruitment of pro-tumoral TAMs, the exclusion of CD8+ T cells from the tumor core, tumor growth, and resistance to anti-PD1 immunotherapy." (PMID 39353903, 2024). "The protein expression level of NLRP3, caspase 1, GSDMD, IL-1β and IL-18 in XRZYBXD high dose group were also significantly higher than those in the tumor model group by WB." (PMID 40046008, 2024). "Cisplatin activates the MEG3/NLRP3/caspase-1/GSDMD pathway to induce pyroptosis in triple-negative breast cancer (TNBC), thereby inhibiting tumor growth and metastasis." (PMID 38654314, 2024). "In present study, compared with tumor model group, the expression of NLRP3, caspase 1, GSDMD and the level of IL-1β and IL-18 in XRZYBXD high dose group were increased." (PMID 40046008, 2024). "Caspase-1, IL-1β, and IL-18 are down-regulated in NSCLC tumor tissues, and simvastatin activates NLRP3-caspase-1-IL-1β and IL-18 pathways to induce pyroptosis and inhibit NSCLC cell migration." (PMID 38654314, 2024). "Here we report that, while inflammasomes have traditionally been described in immune cells, activated caspase-1 is expressed in TNBC cells allowing IL1β maturation, macrophage recruitment, and tumor progression." (PMID 39353903, 2024). "Subsequently, we conducted clustering and LASSO analysis on each tumor and found that the inhibitory and the stimulating immune checkpoints positively correlate with ZBP1, NLRP3, CASP1, CASP8, and TNFAIP3." (PMID 38002938, 2023). "Direct anti-tumor effects of doxorubicin and cisplatin on malignant mesothelioma rely on pyroptosis attributed to increased NLRP3 expression and caspase-1 activation." (PMID 36932407, 2023). "AIM2-/- and caspase 1-/- BMDM, treated with LPS and either dsDNA or tumor CM, similarly produced significantly less IL-1β compared to WT BMDM." (PMID 37449203, 2023). "The results showed that treating a human granulosa-like tumor cell line (KGN) with metformin significantly decreased LPS-induced expression of miR-670-3p, NOX2, NLRP3, ASC, cleaved caspase-1, and GSDMD-N." (PMID 37244286, 2023). "Considering the literature and our experimental results suggesting that the caspase-1/GSDMB axis plays an important role in triggering pyroptosis, we analyzed the expression profiles of the GSDMB and caspase-1 genes in LUAD tumor tissues in the GEPIA database." (PMID 37705753, 2023). "At the molecular level, we used IHC assays for the mouse tumor tissues to test the expression status of NLRP3 and cleaved caspase-1 (pyroptosis related proteins), and found that the combined treatment induced a higher degree of pyroptosis than monotherapy." (PMID 37705753, 2023). "Treatment with caspase-1 inhibitors (YVAD, VADs, and NCX-4016) suppressed lipid accumulation and primary tumor growth for targeting the caspase-1/PPARγ/MCAD pathway in TAM differentiation." (PMID 37426676, 2023). "IL-1β and coculture of tumor cells with macrophages enhances the proliferation of tumor cells which is AIM2 and Casp1/11 dependent." (PMID 37449203, 2023). "IL-1β and coculture of tumor cells with macrophages enhances the proliferation of tumor cells which is AIM2 and caspase 1/11 dependent (Gigure 6)." (PMID 37449203, 2023).
tumor (continued). "In AOM/DSS-induced colon cancer, it has been shown that IL-18 levels were decreased in tumor-bearing mice, that the NLRP3/ASC/CASP1/IL-18 axis was important to dampen tumor growth and this was dependent on IFN-γ production." (PMID 37298187, 2023). "In their study, RT damaged tumor cell DNA, activated AIM2, and subsequently induced caspase-1-GSDMD pathway-mediated pyroptosis, and reduced tumor volume and weight." (PMID 36457125, 2022). "We found that tumor growth was blunted in NLRP3 null mice, which phenocopied the previously demonstrated protective effect found in caspase-1 null mice but was unaltered in AIM2 null mice." (PMID 36439171, 2022). "Immunohistochemistry analysis of tumor xenograft samples suggested that in the radiation-treated group, circNEIL3 knockdown elevated the expression of γH2AX, AIM2, cleaved caspase-1, and GSDMD, but reduced the levels of PIF1 and BRCA1." (PMID 35190532, 2022). "Except for the role of CTSB on tumor cells, there are some reports that CTSB interacting with NLRP3 and to subsequent caspase-1 activation in macrophages." (PMID 36132145, 2022). "It is reported that the NLRP3/caspase-1/GSDMD-dependent pyroptosis is enhanced in NSCLC cells treated with polyphyllin VI, leading to the elimination of tumor cells." (PMID 35819638, 2022). "We confirmed that caspase-1 activity and programmed cell death downstream of the NLRC4 inflammasome increased with tumor malignancy because of Tim-3/Gal-9." (PMID 35216164, 2022). "MEG3 knockdown suppresses the activation effect of DDP on NLRP3/caspase-1/GSDMD pathway-mediated pyroptosis and alters the inhibitory effect of DDP on tumour proliferation and metastasis in triple-negative breast cancer." (PMID 35778526, 2022). "The other paper reported that the higher expression of pyroptosis signaling pathway effectors caspase-1, IL-1beta, and GSDMD was negatively related to tumor size and lymph node metastasis." (PMID 34381023, 2021). "The presence of an anti-tumor drug in the CNFs/5-FU hydrogels determined the activation of inflammasome in MDA/MB 231 and ZR 75-1, which promoted caspase-1 dependent cell death (pyroptosis)." (PMID 34452150, 2021). "Interestingly, the absence of caspase-1 activity in tumor cells was not only associated with decreased mRNA levels of caspase-1 and downstream cytokines IL-18 and IFNγ, but also with upstream inflammasome sensors or regulators, among which NLRC5 is of particular interest." (PMID 33430344, 2021). "Transactivation p73β (TAp73β) has been shown to directly activate the positive transcription of caspase-1 and upregulate the expression of pro-IL-1β mRNA and IL-1β protein, and thus may be important for the regulation of the inflammasomes and inflammation in tumor." (PMID 34602858, 2021). "In summary, three genes in the PRG model (CASP1, CHMP6, and GZMA) is shown to be a protective factor, while the other three genes (CASP4, DHX9, and DFNA5) were defined as tumor-promoting factors." (PMID 34820372, 2021). "Knockdown of MEG3 abolished the activation effect of DDP on NLRP3/caspase-1/GSDMD pathway-mediated pyroptosis, and reversed the suppression of DDP on tumor growth and metastasis ability in vitro and in vivo." (PMID 34326697, 2021). "Taken together, these data suggested that DDP-induced pyroptosis suppressed tumor growth and metastasis via MEG3/NLRP3/caspase-1/GSDMD pathway in a xenograft animal model." (PMID 34326697, 2021). "Taken together, this report suggests that P2Y2R activation by ATP induces tumor invasion and angiogenesis through inflammasome activation, specifically by regulating the inflammasome components NLRC4, ASC, and caspase-1." (PMID 32397236, 2020). "Collectively, these findings show that JQ1 can suppress tumor growth and EMT progression though caspase-1-dependent pyroptosis in vivo." (PMID 32303673, 2020).